GLP1R (glucagon like peptide 1 receptor)
Diseases named in the same sentence as GLP1R in open-access papers (continued):
Sharing a sentence is not in itself a finding about the gene and the disease.
cancer (continued). "However, the relationship between GLP1R activation and cancer is complex, with some studies suggesting protective effects while others indicate potential risks." (PMID 39777709, 2025). "Studies evaluating the relationship between dual (GLP1R and GIP-R) agonists and cancer risk." (PMID 40282969, 2025). "This study was designed to evaluate the prognostic significance of GLP1R expression across various cancer types, with the hypothesis that GLP1R expression might serve as an indicator of certain cancers’ sensitivity to glucagon/GLP-1 signaling." (PMID 39777709, 2025). "For example, reduced regenerative capacity and altered immune function in older adults could influence both the efficacy and safety of GLP-1R agonists in managing cancer outcomes." (PMID 39777709, 2025). "This duality in GLP-1R’s role may reflect the complex interplay between the drug’s metabolic effects, its direct action on cancer cells, and the broader hormonal and environmental context within the body." (PMID 39777709, 2025). "Noted concerns included detection bias, meaning that patients using GLP-1R agonists may be frequently monitored by physicians and more likely to be diagnosed with cancer." (PMID 41178720, 2025). "Further, the impact of GLP-1R agonists on cancer outcomes may vary significantly based on patient age and sex, emphasizing the need to consider age- and sex-specific factors in evaluating their therapeutic use." (PMID 39777709, 2025). "Interestingly, there was a significant increase in GLP-1 receptor (GLP-1R) expression in the cancer cohort (P=0.0031)." (PMID 40902078, 2025). "Cancers arising from these tissues frequently exhibit altered GLP-1R expression." (PMID 39777709, 2025). "In addition to potential uses for cancer prevention, in vivo and in vitro studies have evaluated the use of GLP-1R agonists in combination with current standard-of-care antineoplastic therapeutics." (PMID 39931650, 2024). "Differences in the expression of the GLP1R in different tumors or differential expression between healthy and diseased tissue could partially explain this differential effect on different cancers." (PMID 38201269, 2023). "Finally, in vitro studies have reported potential antiproliferative effects of GLP1R agonists in various cancer cell types." (PMID 37171501, 2023). "The preclinical evidence on the benefits of GLP1R in other types of cancer is sparse and mixed." (PMID 38201269, 2023). "We found little evidence of association of genetically proxied GLP1R or ABCC8 perturbation with cancer risk." (PMID 37171501, 2023). "Whether TRZD could have similar anti-cancer effects through the activation of the GLP-1R/GIPR is yet to be determined." (PMID 36358930, 2022). "Thus, the binding of glucagon to the glucagon-like peptide-1 receptor (GLP-1R) may subvert the system and contribute to hyperglucagonemia and the activation of signalling that may favour cancer." (PMID 40649254, 2025). "Some studies using data from the FDA Adverse Event Reporting System (FAERS) reported a potential increase in cancer risk associated with GLP-1R agonist use; however, these findings are not consistently corroborated in retrospective cohort or randomized controlled trials." (PMID 41178720, 2025). "However, it remains unclear whether the effect of exenatide or other GLP-1R agonists in the AGE-RAGE axis translates to anti-neoplastic effects for the treatment of cancers." (PMID 36358930, 2022). "This study presents a comprehensive analysis of the relationship between GLP1R and GCG expression and overall survival across various cancer types." (PMID 39777709, 2025). "The role of glucagon as a cancer regulator, and the usefulness of the GCGR and GLP1-R as biomarkers are underexplored." (PMID 40649254, 2025). "As a first example, glucagon-like peptide-1 receptor (GLP-1R) agonists used as anti-diabetic treatment were shown to induce preneoplastic lesions and/or cancers in the pancreas and the thyroid." (PMID 23641235, 2013).
cancer (continued). "Some studies document reductions in fasting insulin levels with GLP-1R therapy in cancer settings; however, insulin levels are not always reported." (PMID 41178720, 2025). "In some cancers, such as those in the bladder, increased GLP1R expression may be protective, potentially reflecting a beneficial response to GLP-1R activation." (PMID 39777709, 2025). "We speculate that drugs that target both GLP-1R and GIPR might have better effectiveness against cancers with high expression of both receptors, such as pancreatic, thyroid, breast, and lung cancers." (PMID 41178720, 2025). "In addition, this GLP-1R agonist activates AMPK, inhibiting the proliferation of various cancerous cells, making it a promising cancer treatment." (PMID 38801466, 2024). "Perhaps, GLP-1R is good for those people without cancer by protecting their NSCs and preventing cancer, but not so good for those patients with advanced, fulminant cancer laden with active CSCs." (PMID 38339375, 2024). "The GLP-1R was thus identified in specific endocrine, embryonal, and brain tumors, but virtually not in carcinomas." (PMID 23230431, 2012). "However, the current literature reveals a lack of in vivo studies on specific GLP-1R agonists such as semaglutide, necessitating further research to elucidate its precise mechanisms and effects, particularly in cancer." (PMID 38801466, 2024). "The effect of GLP-1R agonists liraglutide and exendin-4 was examined in vivo on CD-1, MCF-1, MDA-MB-468, MDA-MB-231, 4T1, LNCap, PANC-1, MIA PaCa-2, CT26, SKOV-3, and Apc(Min/+) cell lines expressed in cancers such as thyroid, breast, prostate, pancreatic, colon, ovarian, intestinal, and liver." (PMID 38801466, 2024). "Moreover, embryonal and nervous system tumors show modest GLP-1R expression, whereas most carcinomas, including those commonly affecting the breast, colorectal system, gastric system, and lungs, exhibit minimal or no GLP-1R expression." (PMID 39335195, 2024). "Conversely, carcinomas exhibited a very low or no GLP-1R expression." (PMID 23230431, 2012). "Additionally, given the long induction period of cancers, using MR to examine target-mediated effects of medications that have been on the market for relatively short periods of time (e.g. SGLT2 inhibitors and GLP1R agonists) can be informative in predicting their long-term safety profiles." (PMID 37171501, 2023).
kidney disease (60 papers, 2010 to 2026). "Fourth, emerging treatments such as glucagon-like peptide 1 receptor agonists have shown promise in reducing kidney disease progression risk, and future studies should assess their added benefit in individuals already being treated with SGLT2 inhibitors." (PMID 41206830, 2026). "This genetic association study demonstrated that higher genetic GLP1R expression was associated with a small reduction in risk of kidney disease progression and supported a nephroprotective role of GLP-1RAs." (PMID 39453656, 2024). "Are glucagon-like peptide 1 receptor agonists (GLP-1RAs) associated with kidney disease progression?" (PMID 39453656, 2024). "In this genetic association study, higher GLP1R gene expression was associated with a small reduction in risk of kidney disease progression." (PMID 39453656, 2024). "This genetic association study investigates whether GLP1R gene expression as a proxy for glucagon-like peptide 1 receptor agonists is associated with reductions in kidney disease progression." (PMID 39453656, 2024). "Our study assessed the association between genetically determined GLP1R gene expression in human tissues and kidney disease progression, leveraging the extensive biobank and genetic resources of the US Department of Veterans Affairs (VA) Million Veteran Program (MVP)." (PMID 39453656, 2024). "We studied naturally occurring genetic variation associated with systemic GLP1R expression and tested whether the same variants were also associated with a difference in kidney disease progression when examined on a population-wide scale." (PMID 39453656, 2024). "Pending further clinical studies, the use of a sodium-glucose transport protein 2 inhibitor and/or glucagon-like peptide 1 receptor agonist may provide an effective therapy for patients with PKD whose kidney disease discordance is strongly linked to cardiovascular-kidney-metabolic syndrome." (PMID 40630282, 2025). "GLP-1 receptor (GLP-1R) agonists decrease blood glucose and body weight and reduce rates of cardiovascular and renal disease." (PMID 41774502, 2026). "In the survival analysis of GLP1R gene expression and kidney disease progression, higher genetic GLP1R expression determined by the GRS was associated with a lower risk of reaching the composite kidney outcome." (PMID 39453656, 2024). "VALUE is 20 years old14; in current times patients also take other ARBs,56,57 statins, finerenone, sodium-glucose-cotransporter-2 inhibitors, or glucagon-like peptide-1-receptor agonists, which can improve cardiovascular and kidney outcomes of patients with DM and/or kidney disease." (PMID 40397037, 2025). "In addition, biological sample collection predates the advent of renal disease modifying agents such as sodium glucose cotransporter inhibitor and glucagon like peptide 1 receptor agonists." (PMID 38704028, 2024). "Therefore, a targeted therapy aimed at inhibiting DPP-4 activity or activating GLP-1R signalling may be a prospective approach in the management of renal disorders such as renal microcirculation lesion-induced fibrosis." (PMID 29607314, 2018). "The primary care in T2DM is pharmacological, especially considering the beneficial effects of new antidiabetic classes of drugs (GLP-1R agonists and SGLT2 inhibitors) on the primary and secondary prevention of cardiovascular and kidney diseases." (PMID 34451903, 2021). "Kidney disease-focused primary-outcome trials with sodium-glucose cotransporter-2 inhibitors, glucagon-like peptide-1 receptor agonists, and non-steroidal mineralocorticoid receptor antagonists." (PMID 38275766, 2024). "The present data show a robust induction of Ren1 expression in the vascular smooth muscle cells of the kidney after single and repeated GLP‐1R activation and this renin recruitment may be involved in the effects of GLP‐1R agonist treatment on kidney disease." (PMID 34277961, 2021).
kidney disease (continued). "Sodium–glucose co-transporter 2 inhibitors (SGLT2is) and glucagon-like peptide-1 receptor agonists (GLP-1 RAs) have been shown to reduce the incidence of cardiovascular and kidney disease in people with type 2 diabetes, ostensibly independent of their effects on blood glucose." (PMID 36404375, 2023).
neurodegenerative disease (52 papers, 2012 to 2026). A disorder of the central nervous system characterized by gradual and progressive loss of neural tissue and neurologic function. "The regional distribution of GLP-1R in the human brain aligns with areas affected by neurodegenerative diseases." (PMID 41226780, 2025). "A number of in vivo and in vitro studies using preclinical models of inflammatory and neurodegenerative diseases show that GLP-1 receptor (GLP-1R) activation has anti-inflammatory properties." (PMID 39857716, 2025). "They highlight the need for human-specific studies to accurately assess the therapeutic potential of GLP-1R agonists in neurodegenerative diseases." (PMID 41226780, 2025). "In neurodegenerative disease models, such as Alzheimer’s, GLP-1R agonists have been shown to restore circadian health." (PMID 39518143, 2024). "Therefore, repurposing of FDA-approved GLP-1R agonists with improved pharmacokinetics, could be potential therapeutic strategy for the treatment of neurodegenerative diseases associated with microgliosis and reactive astrogliosis, including AD, PD, PSD, and VCID." (PMID 38659577, 2024). "In much the same way, in our present study, multi-agonists magnified anti-neuroinflammatory and neuroprotective benefits as compared to a single GLP-1R agonist in cell culture models of neurodegenerative disease." (PMID 39062586, 2024). "The discovery of this molecular probe creates a better prospect for applying GLP-1R molecular imaging to neurodegenerative diseases such as PD and AD." (PMID 37780209, 2023). "Fortunately, GLP-1R molecular imaging has been involved in ischemic cardiomyocytes and neurodegenerative diseases." (PMID 37780209, 2023). "Facilitating blood–brain barrier crossing of GLP-1R agonists is sought after for other neurodegenerative diseases." (PMID 36995380, 2023). "Several in vivo and in vitro studies using preclinical models of neurodegenerative diseases show that GLP-1R activation reduces the production of pro-inflammatory cytokines and immune cell infiltration in tissues." (PMID 37333802, 2023). "Several studies in vivo and in vitro using preclinical models of neurodegenerative diseases show that GLP-1R activation has anti-inflammatory properties." (PMID 36076972, 2022). "GLP-1R agonists in animal models of many neurodegenerative diseases repeatedly increased the expression of BDNF in the brain." (PMID 34003475, 2021). "Though several reports have shown the neuroprotective effects of TEN by the upregulation of GLP-1R in neurodegenerative diseases, our findings show that TEN can also induce antinociception and neuroprotection through GLP-1R independent mechanisms." (PMID 34573072, 2021). "Recently, the GLP-1R signaling pathway has emerged as a potential therapeutic target in cardiovascular and neurodegenerative diseases." (PMID 34573072, 2021). "GLP-1R agonists have previously been found efficacious in several animal models of neurodegenerative diseases, including AD and PD, in protecting against neuronal death or degeneration." (PMID 32887883, 2020). "In this article, we review the role of APE1 in neurodegenerative diseases and its relationship to neuroprotective mechanisms of the activated GLP-1 receptor (GLP-1R) in neurodegenerative disorders." (PMID 28846606, 2017). "GLP-1R, therefore, is a potential candidate for developing innovative treatments in cerebral ischemic stroke and neurodegenerative diseases." (PMID 28846606, 2017). "GLP-1R therapeutic benefits and mechanisms in neurodegenerative diseases." (PMID 41226780, 2025). "In addition, our results indicate that these multi-agonists have the potential to outperform commercially available single GLP-1R agonists in neurodegenerative disease treatment." (PMID 39062586, 2024). "This implies that focusing on GLP-1R in astrocytes and microglia may be a viable therapeutic approach for the management of neuropathic pain and neurodegenerative diseases." (PMID 39594606, 2024).
neurodegenerative disease (continued). "Future in vivo studies and clinical trials are certainly warranted to determine whether incretin receptor multi-agonists may outperform single GLP-1R agonists as a novel therapeutic option for human neurodegenerative diseases." (PMID 39062586, 2024). "It is the first report of GLP-1R molecular imaging in patients with neurodegenerative disease, which opens a good direction for the future in this still-unknown field." (PMID 37780209, 2023). "It had been previously observed that glucagon-like peptide-1 receptor (GLP-1R) agonists had neuroprotective effects in neurodegenerative diseases like PD; however, the mechanism was unknown." (PMID 36915214, 2023). "Therefore, GLP-1R agonists may be a potential therapeutic agent for the treatment of neurodegenerative diseases." (PMID 39858999, 2024). "In neurodegenerative diseases, mollugin exhibits significant neuroprotection in endothelial and hippocampal experimental models through the regulation of the BDNF/TrkB and GLP-1R signaling pathways." (PMID 41465430, 2025). "The research on GLP-1R molecular imaging in neurodegenerative diseases and other central nervous system diseases has not achieved more extraordinary breakthroughs, limited to preclinical studies and related studies of blood-brain barrier penetration." (PMID 37780209, 2023). "Interestingly, reduced activity of GLP-1R in the CNS results in microglia activation and reactive astrogliosis, suggesting that activation of GLP-1R by GLP-1R agonist could be a viable strategy to attenuate activation of microglia and astrogliosis in neurodegenerative diseases." (PMID 38659577, 2024).
infection (15 papers, 2019 to 2026). The state of being infected such as from the introduction of a foreign agent such as serum, vaccine, antigenic substance or organism. "Regarding glucose-lowering agents, glucagon-like peptide-1 receptor agonists (GLP-1RAs) are recommended as first-line therapy to mitigate overall infection risk." (PMID 41133232, 2025). "When we determined amounts of GLP-1R at day 80 post infection, we found it already upregulated in TKO-mice, but significantly down-regulated in prion infected WT-mice." (PMID 31118110, 2019). "GLP-1R agonists (GLP-1RAs) have many functions, such as neuroprotection, inhibiting infection, and metabolic regulation, and show good application prospects in improving cognitive function." (PMID 40171533, 2025).
heart disease (13 papers, 2020 to 2026). "Glucagon-like peptide-1 receptor agonists (GLP-1 RAs) are a class of medications originally developed for diabetes but are now used to improve lifespans in those with heart disease and increase weight loss." (PMID 38987347, 2024). "The treatment of advanced heart disease is evolving to include novel medical therapies, such as SGLT-2 inhibitors and glucagon-like peptide-1 receptor agonists." (PMID 38540200, 2024).
psychiatric disorder (13 papers, 2018 to 2026). A disorder characterized by behavioral and/or psychological abnormalities, often accompanied by physical symptoms. "There is growing scientific interest in the potential role of glucagon-like peptide-1 receptor agonists (GLP-1RAs) as an effective therapeutic strategy for sustainable weight loss in patients with psychiatric disorders." (PMID 41230025, 2025). "Characteristics of glucagon-like peptide-1 receptor agonist (GLP-1 RA)-associated psychiatric disorders: adverse event (AE) reports sourced from the FDA Adverse Event Reporting System (FAERS) database (Q1 2004–Q1 2023)." (PMID 38390214, 2024). "We systematically assessed genetic variation in the GLP1R locus for impact on mental ill‐health (MIH) and cardiometabolic phenotypes across diverse populations within UK Biobank." (PMID 39838854, 2025). "There are reports of improvements in lifestyle factors such as reduced smoking; however, clinical assessment of changes in MIH is yet to be adequately assessed to confirm the role that GLP1R may play in mental illness." (PMID 39838854, 2025). "Emerging evidence suggests that glucagon-like peptide-1 receptor (GLP1R) agonists may have potential benefits for mental illnesses." (PMID 40141382, 2025).
neurological disorders (12 papers, 2013 to 2025). "Evidence suggests that GLP-1R agonists positively affect neurons, promote neurogenesis, reduce apoptosis and oxidative stress, and decrease neuroinflammation in many neurological disorders." (PMID 38732190, 2024). "GLP-1R activation in microglia has been shown to have a palliative effect on neuroinflammation in various neurological diseases 39-41." (PMID 35280691, 2022). "Emerging evidence reveals that downstream signaling pathways of GLP-1R play a pivotal role in neuroprotection in various neurological disorders." (PMID 28846606, 2017). "The GLP-1R is expressed in several regions of rodent and human brain areas, supporting the use of CNS mediated GLP-1 receptor agonists for treatment of human neurological disorders." (PMID 24312624, 2013).